IL31 (interleukin 31)
Diseases named in the same sentence as IL31 in open-access papers (continued):
Sharing a sentence is not in itself a finding about the gene and the disease.
psoriatic arthritis (4 papers, 2020 to 2026). Joint inflammation associated with psoriasis. "Ninety pediatric participants (JIA, CD, psoriatic arthritis, healthy controls) underwent serum cytokine profiling (IL-1α, IL-1β, IL-36α, IL-37, IL-6, IL-18, IL-27, IL-31) at baseline and 12 months." (PMID 42196228, 2026).
systemic lupus erythematosus (4 papers, 2017 to 2023). An autoimmune multi-organ disease typically associated with vasculopathy and autoantibody production. "In particular, systemic lupus erythematosus (SLE) patients carrying rs7977932 G allele in IL-31 have the high-level protein of IL-31 in serum." (PMID 29484036, 2018). "In systemic lupus erythematosus (SLE) IL-31 serum levels were not shown to be significantly increased compared to healthy controls." (PMID 31281316, 2019).
systemic sclerosis (4 papers, 2021 to 2025). A chronic disorder, possibly autoimmune, marked by excessive production of collagen which results in hardening and thickening of body tissues. "IL-31 directly promotes collagen production in dermal fibroblasts, thereby promoting fibrosis and Th2 polarization in systemic sclerosis." (PMID 40843362, 2025). "Previous studies have found that IL-31 is overexpressed in dermal fibroblasts of patients with systemic sclerosis, which is characterized by fibrosis and autoimmune dysfunction." (PMID 40843362, 2025). "Th2-specific Il-31 expression was increased in skin of the bleomycin-treated SARAWT mice and patients with scleroderma (or systemic sclerosis, SSc)." (PMID 36136606, 2022). "Indeed, high levels of IL-31 were reported in plasma, fibrotic skin and lung lesions of systemic sclerosis (SSc) patients." (PMID 33644104, 2021).
chronic kidney disease (3 papers, 2022 to 2025). Impairment of the renal function secondary to chronic kidney damage persisting for three or more months. "IL-31 Antagonism & Edema Monitoring: Nemolizumab’s IL-31 pathway blockade may benefit atopic phenotypes but necessitates intensified fluid retention monitoring during treatment initiation, especially in patients with chronic kidney disease or heart failure." (PMID 41312463, 2025).
colon carcinoma (3 papers, 2017 to 2025). "We chose to work with MC38 and CT-26 colon carcinoma cells that highly express both IL31 and IL31RA." (PMID 28147314, 2017). "MC38 murine colon carcinoma cells depleted of IL31 exhibit an increase in invasive and migratory properties in vitro, effects that are reversed by supplementing the cells with exogenous IL31." (PMID 28147314, 2017). "To investigate the possible role of IL31 in tumor cells, we silenced IL31 expression in MC38 murine colon carcinoma cells that highly express IL31 using siRNA (siIL31)." (PMID 28147314, 2017). "For instance, murine colon carcinoma cells without IL-31 have greater invasive, migratory, and tumor growth properties, while these effects can be reversed by supplementing exogenous IL-31 to the cells." (PMID 29484036, 2018).
diabetes mellitus (3 papers, 2015 to 2025). A metabolic disorder characterized by abnormally high blood sugar levels due to diminished production of insulin or insulin resistance/desensitization. "Following the adjustment for confounders, including sex, age, cardiovascular disease, diabetes mellitus, medication status, and infection, both the SII and IL-31 metrics remained statistically significant in the model 2 and model." (PMID 41169429, 2025).
gastric cancer (3 papers, 2020 to 2025). A primary or metastatic malignant neoplasm involving the stomach. "To clarify the effect of FAP on IL-31 expression in CAFs cells, we isolated CAFs from two gastric cancer tissues and further upregulated FAP expression in CAFs using lentiviral vectors." (PMID 40843362, 2025). "Here, our study uncovers a novel mechanism of CAF-mediated immune evasion in gastric cancer: FAP+CAFs facilitate the transition of naive CD4+ T cells toward a Th2 phenotype through IL-31 secretion." (PMID 40843362, 2025). "The results showed that IL-31 significantly reduced the therapeutic effectiveness of PD-1 blockade in MFC-derived gastric cancer xenografts." (PMID 40843362, 2025). "In summary, our results reveal a novel mechanism by which IL-31 secreted by FAP+CAFs drives immune evasion in gastric cancer." (PMID 40843362, 2025). "CCL5, CCL22, CCL21, CCL2, and CCL15 were correlated with effector memory CD4 T cell in T1/T2 stage gastric cancer, and the number of cells was associated with the expression of IL3, IL17F, IL18, IL22, and IL31." (PMID 33426088, 2020). "The results showed that FAP+CAFs may impair the efficacy of anti-PD-1 therapy in gastric cancer mice, and that IL-31 blockade can partially restore treatment sensitivity, potentially by alleviating the immunosuppressive effects associated with FAP+CAFs." (PMID 40843362, 2025). "This explanation is supported by the observed correlation between reduced circulating IL-31 and local mucosal IL-31 in gastric cancer, further supporting that both local and systemic host immunities contribute to the progression of malignancies among the susceptible individuals." (PMID 36405715, 2022). "Our findings further demonstrate that IL-31 derived from FAP+CAFs promotes the polarization of naive CD4+ T cells toward the Th2 phenotype, thereby establishing an immunosuppressive TME and facilitating gastric cancer immune evasion." (PMID 40843362, 2025). "In addition, to determine whether IL-31 directly promotes gastric cancer cell proliferation, we further incubated MFC cells with recombinant murine IL-31 and assessed its effect using the CCK-8 assay." (PMID 40843362, 2025). "This study reveals a novel mechanism driving immune evasion in gastric cancer, proposes FAP+CAFs as a potential biomarker for predicting anti-PD-1 therapy resistance, and suggests that targeting the IL-31/STAT6 axis could offer new therapeutic strategies to enhance immunotherapy efficacy." (PMID 40843362, 2025).
Hodgkins lymphoma (3 papers, 2017 to 2022). A heterogeneous group of malignant lymphoid neoplasms of B-cell origin characterized histologically by the presence of Hodgkin and Reed-Sternberg (HRS) cells in the vast majority of cases. "Additionally, in published studies concerning the level of IL-31 in different conditions, e.g., Hodgkin lymphoma, the same phenomenon was observed." (PMID 35324695, 2022).
scabies (3 papers, 2020 to 2024). "A hallmark symptom of scabies is severe itch which may be associated with the generation of a pruritogenic cytokine, interleukin (IL)-31 generated by M2 macrophages in ordinary scabies lesions." (PMID 33292572, 2020). "As a cytokine that acts upon a certain number of cells’ subpopulations, IL-31 was researched in systemic conditions such as sepsis, respiratory diseases, and HBV, beyond the well-known pruritogenic role that it plays in itching diseases such as scabies." (PMID 35742951, 2022).
vitamin D deficiency (3 papers, 2014 to 2024). A nutritional condition produced by a deficiency of VITAMIN D in the diet, insufficient production of vitamin D in the skin, inadequate absorption of vitamin D from the diet, or abnormal conversion of vitamin D to its bioactive metabolites. "Further research could also consider the effect of TLR7 on other pathways involved in the amplification of the Th2 response, such as IL-13, IL-31, and IL-33 cytokines, vitamin D deficiency, and changes in the lung microbiome, in the context of chronic respiratory disease." (PMID 39769461, 2024). "Particularly, we suggest that since IL-31 is likely to be expressed by a number of cells in the allergic situations in which IL-4 is present and promotes Th2-driven inflammation, it contributes in allergic reaction involving the vitamin D deficiency only partially." (PMID 25061262, 2014).
Alzheimer disease (2 papers, 2014 to 2020). A progressive, neurodegenerative disease characterized by loss of function and death of nerve cells in several areas of the brain leading to loss of cognitive function such as memory and language. "We can hypothesize that, in PLCA, a functional decrease in OSMRß and IL-31 RA signaling pathway may cause an increase in signaling through type I OSM complex (LIF receptor and gp130), which may lead to a peripheral neurodegenerative condition like Alzheimer's disease." (PMID 25054142, 2014).
autoimmune uveitis (2 papers, 2022 to 2024). An autoimmune form of uveitis (disease). "However, the precise role of the IL-33/IL-31 axis in equine recurrent uveitis (ERU) and autoimmune uveitis remains unclear and warrants further investigation." (PMID 39519064, 2024).
bladder cancer (2 papers, 2023 to 2024). "An initial screen included a bladder cancer panel with 16 proteins (MCP‐1, MIP‐1α, MIP‐1β, IP‐10, IFN‐α, IL‐1α, IL‐1RA, IL‐8, IL‐7, IL‐31, IL‐15, TNF‐β, Eotaxin, SDF‐1α, Rantes, and GRO)." (PMID 38553868, 2024). "Furthermore, a recent study performing whole exome sequencing of patients with bladder squamous cell carcinoma, also displayed significantly higher expression of OSM, OSMRβ, and IL-31, suggesting both OSM-OSMR and IL-31-OSMR signaling may impact bladder cancer progression." (PMID 37841259, 2023).
Cirrhosis (2 papers, 2022). A chronic disorder of the liver in which liver tissue becomes scarred and is partially replaced by regenerative nodules and fibrotic tissue resulting in loss of liver function. "Moreover, TGF-β1 and IL-31 are associated with the progression of chronic hepatitis B to cirrhosis and are closely related to the severity of hepatitis B virus-related liver cirrhosis (HBV-LC)." (PMID 36117587, 2022). "Nonetheless, a study investigating the association between TGF-β1/IL-31 and stages of chronic HBV infection showed that TGF-β1 and IL-31 are linked to the progression from chronic hepatitis to cirrhosis and correlate with the severity of cirrhosis." (PMID 35742951, 2022). "In patients with HBV-related cirrhosis, serum TGF-β1 and IL-31 were significantly elevated, with sensitivity and specificity of 90.9% and 66.7%, respectively." (PMID 36117587, 2022).
colitis (2 papers, 2025). Inflammation of the colon. "Eosinophils are a significant source of IL-31 and IL-17, which, beyond their roles in allergic inflammation, also contribute to the deterioration of colitis at higher levels by intensifying eosinophil-driven inflammation." (PMID 40333150, 2025). "In addition, DSS-induced colitis mice treated with TcES showed a significant increase in the production of IL-4 and the chemokine MCP-1 (CCL2), along with increased production of IL-22 and IL-31, both of which are cytokines involved in protecting the epithelial barrier." (PMID 40576745, 2025).
dilated cardiomyopathy (2 papers, 2017 to 2018). Cardiomyopathy which is characterized by dilation and contractile dysfunction of the left and right ventricles. "Recent data show that the level of IL-31 mRNA in white blood cells is increased in dilated cardiomyopathy (DCM) patients, associated with a lower frequency of the CA/AA at rs4758680, in IL-31." (PMID 29484036, 2018).
endometriosis (2 papers, 2022 to 2024). The growth of functional endometrial tissue in anatomic sites outside the uterine body. "A non-invasive diagnostic test for endometriosis using the antibody array approach was conducted, and IL-31 showed potential as a possible biomarker for endometriosis." (PMID 38337827, 2024). "Validation was performed for 10 proteins, and only IL-31 was confirmed as a possibly useful biomarker for endometriosis." (PMID 35743637, 2022).
epithelial ovarian cancer (2 papers, 2018 to 2022). "Results from our present investigation indicate the significant association of the SNPs rs7977932 and rs4758680 in IL-31 with the development of epithelial ovarian cancer in a Chinese population." (PMID 29484036, 2018). "Single nucleotide polymorphisms (SNPs) in IL-31 provide us with an opportunity to investigate potential effects of the factor in the development and progression of epithelial ovarian cancer in humans." (PMID 29484036, 2018). "It indicates that the CG/GG may be associated with the protective effect of IL-31 against the development of the epithelial ovarian cancer." (PMID 29484036, 2018). "A lower recurrence risk of the epithelial ovarian cancer in patients with the CG/GG genotypes may represent the potential antiangiogenic effect of IL-31 since tumor growth is highly dependent on angiogenesis." (PMID 29484036, 2018). "Our findings suggested that rs7977932 and rs4758680 of IL-31 may be associated with the development and progression of the epithelial ovarian cancer in the Chinese population." (PMID 29484036, 2018). "Taken all these findings together, it indicates that the CG/GG associated with the increased expression of IL-31 may have an antiepithelial ovarian cancer effect in a Chinese population." (PMID 29484036, 2018). "However, there is no information of the polymorphisms, rs7977932 and rs4758680 of IL-31, in epithelial ovarian cancer patients." (PMID 29484036, 2018). "Roles of interleukin-31 (IL-31) in the development and progression of human epithelial ovarian cancer are largely unknown." (PMID 29484036, 2018). "Thus, the increased level of IL-31 by the genotypes of the CG/GG may contribute to the reduction of the epithelial ovarian cancer severity." (PMID 29484036, 2018). "Switching to ovarian cancer, the JNK-STAT pathway in tumor invasion and metastasis is activated by IL-31 in the overexpressing, tumoral cells (IL-31RA+), with a possible correlation with different clinical presentation and prognosis." (PMID 35742951, 2022). "IL-31 and its receptor, IL31RA, are highly expressed in tumor specimens from ovarian cancer patients and other human and mouse cancer cell lines." (PMID 29484036, 2018).
Fever (2 papers, 2023). Body temperature elevated above the normal range. "Therefore, we examined the comparative effects of IL-31 and loxoprofen on TNCB-induced fever (surface body temperature) and swelling (cutaneous weight) in mice." (PMID 37511321, 2023). "Based on this study, an involvement of IL-31 in the pathogenesis of the Th-2 mediated immune response in SRMA and also in MUO can be assumed; in particular, the systemic changes in SRMA like generalized arteritis and the proinflammatory status (pyrexia, leukocytosis) can be well explained in SRMA." (PMID 37627467, 2023).
infestation (2 papers, 2022 to 2023). "Finally, regarding the evident role of Th2-oriented response in parasitic infections, IL-31 has been studied also in gastrointestinal colonization and pulmonary infections." (PMID 35742951, 2022).
Kawasaki disease (2 papers, 2014 to 2018). A rare inflammatory disease characterized by an acute febrile, systemic, self-limiting, medium-vessel vasculitis primarily affecting children. "As far as cardiovascular diseases are concerned, the involvement of IL-31 has been studied in Kawasaki's disease." (PMID 29713240, 2018). "In particular, a study demonstrated how IL-31 expression was related to Kawasaki's disease, and thus, its higher expression could be considered as a promoter of coronary lesions." (PMID 29713240, 2018). "For the first time, our present study provides evidence that IL-31 expression is closely related to Kawasaki disease, and that it may also be a predictor of CAL formation." (PMID 25122210, 2014).
liver cirrhosis (2 papers, 2021 to 2023). "Of note, the IL-31 pathway has also been reported to be involved in the pathogenesis of hepatitis B virus-related liver cirrhosis, potentially suggesting a wider role for IL-31 in hepatic health." (PMID 33644103, 2021).
melanoma (2 papers, 2017 to 2021). A malignant, usually aggressive tumor composed of atypical, neoplastic melanocytes. "The levels of IL-6, IL-8, IL-10, IL-17A, IL-27, IL-31, GM-CSF, IFN-α, IL-9, VEGF-D, TNF-β, NGFβ, IL-23, IL-22, and IL-1α were below the threshold of detection in both melanoma patients and healthy controls." (PMID 33574842, 2021). "The mRNA and protein levels of IL31 and IL31RA were evaluated in cell lysates derived from myeloma, leukemia, melanoma, glioblastoma, and several carcinoma cell lines of both mouse and human origins." (PMID 28147314, 2017).
mycosis fungoides (2 papers, 2021 to 2022). Classical mycosis fungoides is the most common type of mycosis fungoides (MF), a form of cutaneous T-cell lymphoma, and is characterized by slow progression from patches to more infiltrated plaques and eventually to tumors. "Levels of IL-31 in the sera of patients suffering from mycosis fungoides (MF) and Sézary syndrome (SS), the most frequent forms of CTCL, were found to be higher than in healthy controls, and higher levels of IL-31 were related to disease severity." (PMID 35742951, 2022). "We investigated IL31 serum levels in different subtypes of CTCL, including Mycosis Fungoides (MF) (typically not pruritic), Folliculotropic Mycosis Fungoides (FMF) and Sézary syndrome (SS) (both often pruritic)." (PMID 34027133, 2021).
sarcoidosis (2 papers, 2015 to 2017). Sarcoidosis is a multisystemic disorder of unknown cause characterized by the formation of immune granulomas in involved organs. "Vitreous levels of IL-4, IL-17A, IL-22, IL-31, and TNFα in PDR patients were also significantly higher than those of sarcoidosis patients." (PMID 26352837, 2015).
scleroderma (2 papers, 2021 to 2022). Scleroderma is a rare autoimmune connective tissue disorder characterized by abnormal hardening of the skin and, sometimes, other organs. "Importantly, a recent published study suggests a significant increase in IL-31 levels in plasma, fibrotic skin, and lung lesions of patients with scleroderma compared to healthy controls." (PMID 33815402, 2021).
Sepsis (2 papers, 2022). Sepsis is defined as life-threatening organ dysfunction caused by a dysregulated host response to infection. "IL-31 was able to reduce the mortality rate of lipopolysaccharide (LPS)-induced sepsis, by a reduction in the inflammatory cytokines and inhibition of IL-1β production in LPS-induced sepsis." (PMID 35742951, 2022). "Lower levels of IL-31 are characteristic of sepsis, when compared to SIRS, and even lower levels in the case of septic shock, showing sensitivity up to 80%." (PMID 35742951, 2022). "A panel of combined markers further yielded 100% sensitivity and specificity, suggesting that the combination of IL-31, IL-1β, and NLRP3 may provide a promising diagnostic and prognostic panel for sepsis." (PMID 35967871, 2022). "IL-31 targeting has proven to be a safe and convenient method to treat itching, and it also has shown some potential in treating oncological diseases and a plethora of inflammatory conditions that could lead to organ failures, such as hepatitis and sepsis." (PMID 35742951, 2022). "Thus, arguably, systemic-inflammatory-response syndrome (SIRS) and sepsis could be differentiated by the measurement of IL-31, IL-1ß, and NLRP3." (PMID 35742951, 2022). "In human cells, neutralization via antibodies against IL-31 and its receptor enhanced NLRP3 expression and IL-1β activation, suggesting that the inflammasome plays a role in sepsis development." (PMID 35742951, 2022).
viral infections (2 papers, 2022 to 2024). "It seems that the immune response was normal outside the viral infections, and no minimal variation in IL-10 and IL-31 was noticed in the end of the study." (PMID 38397331, 2024).
vitiligo (2 papers, 2024 to 2025). Generalized well circumscribed patches of leukoderma that are generally distributed over symmetric body locations and is due to autoimmune destruction of melanocytes. "Meanwhile, there is mounting evidence that the immunological milieu of vitiligo is also characterized by cytokines connected to other Th2 cell responses, such as IL-4, IL-5, IL-10, IL-13, and IL-31, rather than just Th1 cells and related cytokines (IFN-γ, TNF-α, and IL-2)." (PMID 38695020, 2024).